SDHA (succinate dehydrogenase complex flavoprotein subunit A)
Diseases named in the same sentence as SDHA in open-access papers (continued):
Sharing a sentence is not in itself a finding about the gene and the disease.
lung adenocarcinoma (3 papers, 2015 to 2019). A carcinoma that arises from the lung and is characterized by the presence of malignant glandular epithelial cells. "While association of SDHA copy number variation to prognosis was found in lung squamous cell carcinoma, we have found no literature exploring the connection of SDHA to lung adenocarcinoma." (PMID 30704450, 2019). "The genes CEP72, BRD9, TRIP13, SLC9A3, SDHA, SLC6A19 and PDCD6 did not have any predictive role in lung adenocarcinoma prognosis." (PMID 26497366, 2015).
lung carcinoma (3 papers, 2023 to 2024). "MUC16, PRX, and SDHA showed the highest frequency of deleterious mutations, occurring in all primary lung cancers and BMs (Case 2, Case 3, Case 5, and Case 7)." (PMID 37384291, 2023). "In this study, we found that MUC16, PRX, and SDHA showed a high frequency of deleterious mutations in all primary lung cancers, and BMs inherited the genomic variations, which indicated those genes may act as lung cancer cell dissemination driver genes." (PMID 37384291, 2023). "In lung cancer, the TCA cycle is restored by the upregulation of SDHA and valine metabolism." (PMID 36982149, 2023). "There are no definitive reports on the relationship between SDHA and TRIO and lung cancer at present." (PMID 39669196, 2024).
non-small cell lung carcinoma (3 papers, 2021 to 2025). A group of at least three distinct histological types of lung cancer, including non-small cell squamous cell carcinoma, adenocarcinoma, and large cell carcinoma. "In this study, disordered metabolism in non-small cell lung cancer was demonstrated by increased G6PD and SDHA protein levels via immunofluorescence, and up-regulated lactate dehydrogenase was found to be associated with poor prognosis." (PMID 34150616, 2021).
optic atrophy (3 papers, 2017 to 2025). A disorder characterized by loss of optic nerve fibers. "Complex II (succinic dehydrogenase, SDH) deficiency due to heterozygous mutations in the SDHA gene leads to bilateral optic atrophy, cerebellar atrophy, polyneuropathy, psychiatric involvement, and cardiomyopathy." (PMID 33806088, 2021). "More recently, an additional case of childhood onset bilateral optic atrophy and cognitive impairment caused by a heterozygous mutation in SDHA has been described." (PMID 33806088, 2021).
ovarian tumors (3 papers, 2022 to 2025). "In this study, we identified a mitochondrial enzyme succinate dehydrogenase SDHA as a key protein associated with an elevated mitochondrial metabolism in ovarian tumors." (PMID 36291881, 2022). "Altogether, our proteomics data highlight the significance of the TCA cycle metabolic pathway coupled with ETC in supporting the metabolic requirements of SDHA-overexpressing ovarian tumors." (PMID 40563592, 2025). "Using this approach, shikonin emerged as the most effective agent in selectively eliminating SDHA-overexpressing ovarian tumor cells." (PMID 40563592, 2025). "In this study, the primary finding from the proteomic and metabolomic analyses revealed that the TCA cycle pathway plays an important role in ovarian tumors with the SDHA-gain-of-function phenotype." (PMID 40563592, 2025). "SDHA overexpression significantly induced orthotopic ovarian tumor growth, reducing mouse survival." (PMID 40563592, 2025). "However, here, we showed that the SDHA-overexpressing ovarian tumors rely on increased oxidative metabolism of αKG, promoting OXPHOS rather than de novo lipid biosynthesis." (PMID 40563592, 2025). "In addition, SDHA overexpression was demonstrated to improve survival of ovarian tumor cells and their ability to generate colonies in anchorage-independent conditions, thus favoring the spreading of these tumor cells." (PMID 39030377, 2024). "Interestingly, in vitro and in vivo studies have demonstrated a profound anti-tumor efficacy and selectivity of shikonin (an anti-metabolic compound) towards SDHA overexpressing ovarian tumor cells, superior to that observed with chemotherapy." (PMID 39030377, 2024). "Importantly, the percentage (23.5%) of SDHA-high PDX tumors in our data set is consistent with the percentage (19%) of ovarian tumors harboring amplification and/or overexpression of SDHA in patients population (TGCA data set)." (PMID 36291881, 2022). "Our in vivo data demonstrated that pharmacological blocking of LRPPRC’s function results in a long-term therapeutic benefit and can be an effective therapy in SDHA- and LRPPRC-overexpressing ovarian tumors." (PMID 40563592, 2025). "Importantly, our in vivo data showed that pharmacological inhibition of LRPPRC results in a lasting therapeutic benefit and can be an effective therapy in SDHA- and LRPPRC-overexpressing ovarian tumors." (PMID 40563592, 2025).
sarcoma (3 papers, 2021 to 2025). A usually aggressive malignant neoplasm of the soft tissue or bone.
acute myeloid leukemia (2 papers, 2022 to 2023). Acute myeloid leukemia (AML) is a group of neoplasms arising from precursor cells committed to the myeloid cell-line differentiation. "The DNA hypomethylating agent azacytidine, in combination with the BCL-2 inhibitor venetoclax, suppresses Complex II activity by reducing sdhA glutathionylation, which inhibits OXPHOS activity in acute myeloid leukemia stem cells (AML LSCs)." (PMID 36612059, 2022).
bladder cancer (2 papers, 2016 to 2022). "Accordingly, seven of the most commonly used reference genes (ACTB, GAPDH, HPRT, B2M, SDHA, TBP, and 18S) were amplified in the three bladder cancer cell lines exposed to normoxia and hypoxia." (PMID 27835695, 2016).
breast tumor (2 papers, 2013 to 2015). "The SDHA/SDHB expression phenotypes in these 712 breast tumors were, in order of frequency, SDHA(+)/SDHB(+) > SDHA(-)/SDHB(–) > SDHA(-)/SDHB(+) > SDHA(+)/SDHB(–)." (PMID 23888270, 2013).
colon cancer (2 papers, 2023 to 2025). "We investigated the protein palmitoylation of two well-known S-palmitoylated proteins, calnexin and succinate dehydrogenase complex flavoprotein subunit A (SDHA), in human colon cancer cells (HCT-116) using two different detection methods." (PMID 39860245, 2025). "According to the PDC database, compared with normal tissues, SDHA (p < 2.2×10-16), SDHB (p = 1.1×10-13), SDHC (p = 1.2 ×10-10), and SDHD (p = 0.00028) were low expressed in colon cancer at protein level." (PMID 36949947, 2023).
colorectal cancer (2 papers, 2020 to 2022). A primary or metastatic malignant neoplasm that affects the colon or rectum. "Using multigene panel testing, we found several novel germline mutations that have been rarely reported in hereditary colorectal cancer (e.g., ERCC4, SDHA, and XRCC2), but our limited sample size hindered us from determining their penetrance and relationship with colorectal cancer." (PMID 33194656, 2020). "SIRT5 can not only demalonylate and inactivate SDHA to cause multidrug resistance in wild-type Kras colorectal carcinomas (CRCs) but also mediate TPI demalonylation and impair its formation and activity, causing recurrence of mutant Kras CRC." (PMID 35428309, 2022).
endometrial carcinoma (2 papers, 2024). A malignant tumor arising from the epithelium that lines the cavity of the uterine body. "Concerning SdhA and UBAP2L, their involvement in the regulation of stemness-associated markers must be explored in endometrial cancer, which may reveal potential therapeutic targets." (PMID 38893151, 2024). "Proteomic analysis revealed 105 common proteins altered in ECC-1 and RL95-2 cells upon DEAB treatment, suggesting ALDH18A1, SdhA, and UBAP2L as potential markers for endometrial cancer." (PMID 38893151, 2024). "Although not commonly observed in TCs, SDHA amplifications were recently observed in endometrial carcinomas (ECs), and was also found to be co-amplified with TERT in 61% of TERT amplified ECs." (PMID 39030377, 2024). "Furthermore, ALDH18A1, SdhA, and UBAP2L should be explored as novel molecular targets for endometrial cancer." (PMID 38893151, 2024). "Moreover, it was possible to identify three proteins as potential biomarkers for endometrial cancer, namely, ALDH18A1, SdhA, and UBAP2L." (PMID 38893151, 2024). "Additionally, DEAB modulates the expression of certain proteins, namely, ALDH18A1, SdhA, and UBAP2L, identified in endometrial cancer, which might be promising prognostic and therapeutic targets." (PMID 38893151, 2024).
goiter (2 papers, 2014 to 2020). Enlargement of the thyroid gland usually caused by lack of iodine in the diet, hyperthyroidism, or thyroid nodules. "In conclusion, the results of the present study suggest that ACTB gene is more stable than SDHA, GAPDH, HPRTI, YWHAZ, and B2M when evaluating human normal thyroid and goiter together." (PMID 24900955, 2014). "The genes with the lowest variations in expression for normal samples, goiter, and all samples were, respectively, GAPDH, ACTB, SDHA and ACTB, when evaluated by the NormFinder." (PMID 24900955, 2014). "Considering these criteria, none of the selected genes could be used to normalize RT-qPCR data for goiter tissues, and GAPDH and SDHA could be used for normal thyroid." (PMID 24900955, 2014).
graft versus host disease (2 papers, 2023 to 2025). An immune system disorder that occurs after allogeneic hematopoietic stem cell transplant and is a reaction of donor immune cells against host tissues. "In CD4+ T cells, SDHA loss dampened both oxidative phosphorylation (OXPHOS) and glycolysis, impaired cytokine production, proliferation, and reduced CD4+ T cell–mediated graft-versus-host disease after allogeneic stem cell transplantation (SCT)." (PMID 41392980, 2025).
head and neck squamous cell carcinoma (2 papers, 2022 to 2025). A squamous cell carcinoma that arises from any of the following anatomic sites: lip and oral cavity, nasal cavity, paranasal sinuses, pharynx, larynx, and salivary glands. "In head and neck squamous cell carcinoma (HNSCC), the expression of SDHA is higher in the tumor tissues than in the tissue-matched normal mucosa, predicting a higher locoregional recurrence." (PMID 36276638, 2022).
Huntington disease (2 papers, 2016 to 2018). Huntington disease (HD) is a rare neurodegenerative disorder of the central nervous system characterized by unwanted choreatic movements, behavioral and psychiatric disturbances and dementia. "For example, the activity of succinate dehydrogenase was decreased in ST of a Huntington’s disease rat model, and the expression of SDHA was reduced in dopaminergic substantia nigra neurons from PD patients." (PMID 27788166, 2016).
hypertrophic cardiomyopathy (2 papers, 2021 to 2023). A condition in which the myocardium is hypertrophied without an obvious cause. "This includes, on the rarer end of the phenotypic spectrum, hypertrophic cardiomyopathy, which is observed in individuals with biallelic variants in DLD, SDHA, SDHB, and SDHD." (PMID 38031187, 2023).
oral cancers (2 papers, 2011 to 2023). "Cancer and normal regions in tissue sections from oral cancer patients were delineated by a board-certified pathologist, and comparisons of SDHA and succinate dehydrogenase subunit B (SDHB) levels in each region were determined." (PMID 37945749, 2023).
pheochromocytoma and paraganglioma (2 papers, 2017 to 2021). "The majority of hereditary pheochromocytoma and paraganglioma (PPGL) is caused by germline mutations in the SDHB, SDHC, or SDHD genes, which encode three (SDHB, SDHC, SDHD) of five subunits of succinate dehydrogenase (SDH) enzyme (SDHA, SDHDB, SDHC, SDHD, SDHAF2)." (PMID 34356532, 2021).
varicocele (2 papers, 2020 to 2024). A condition characterized by the dilated tortuous veins of the spermatic cord with a marked left-sided predominance. "In unilateral varicocele patients, we observed the overexpression of SDHA protein in comparison to bilateral varicocele, further validating more functional impairment of spermatozoa in the bilateral varicocele group." (PMID 32365753, 2020). "In addition, the acetylation status of proteins, such as HIST1H2B, PRDX1, SDHA, and SOD1, can serve as a biomarker for PTM defects pertaining to the acetylation process in the ejaculated spermatozoa of varicocele patients." (PMID 32365753, 2020).
Wilms tumor (2 papers, 2021 to 2023). An embryonal neoplasm characterized by the presence of epithelial, mesenchymal, and blastema components. "Two of the 59 patients (3%) with Wilms’ tumor carried pathogenic variants in BRCA2 and SDHA." (PMID 33674644, 2021).
-deficient (1 paper, 2018). "Succinate dehydrogenase-deficient RCC is rare and results from inherited germline mutations in the succinate dehydrogenase (SDH) gene, most commonly SDHB but also in SDHA, SDHC and SDHD." (PMID 30123932, 2018).
acute leukemia (1 paper, 2022). A clonal (malignant) hematopoietic disorder with an acute onset, affecting the bone marrow and the peripheral blood. "Further analysis using clinical datasets demonstrated that the elevated expression of a three-gene signature, consisting of SDHA, IDH3A, and ANXA11, was significantly associated with poor survival of acute leukemia patients." (PMID 35463978, 2022).
adenoma (1 paper, 2017). A neoplasm arising from the epithelium. "Immunostaining with SDHA and SDHB antibodies is a valuable diagnostic tool to screen adenomas prior to requesting genetic analysis." (PMID 28284009, 2017).
allergic disease (1 paper, 2025). An immune response that occurs following re-exposure to an innocuous antigen, and that requires the presence of existing antibodies against that antigen. "Similarly, in autoimmune and allergic diseases that are CD4+ T cell–dependent, T-helper polarization, or in MHC class II–restricted diseases, SDHA inhibition could mitigate autoimmune/allergic disorders." (PMID 41392980, 2025).
autoimmune disease (1 paper, 2019). A disorder resulting from loss of function or tissue destruction of an organ or multiple organs, arising from humoral or cellular immune responses of the individual to their own tissue constituents. "SDHA mutation positivity, neoplasms and autoimmune diseases present in the family and patient." (PMID 30854332, 2019).
bone tumors (1 paper, 2023). "In bone tumors, the MSKCC cohort had significantly fewer mutations in MAP3K1, CREBBP, MCL1, GNAQ, MEF2B, MYCN, SDHA, and SMARCA4." (PMID 37546405, 2023).
central nervous system germinoma (1 paper, 2022). A malignant germ cell tumor arising from the central nervous system. "In the present case, for the first time, we report a Chinese CNS germinoma patient with a KIT hotspot somatic mutation concurrent with a novel SDHA germline mutation that showed distinct early-onset." (PMID 35651799, 2022).
Cerebellar atrophy (1 paper, 2021). Cerebellar atrophy is defined as a cerebellum with initially normal structures, in a posterior fossa with normal size, which displays enlarged fissures (interfolial spaces) in comparison to the foliae secondary to loss of tissue. "Progressive cerebellar atrophy in a patient with complexes II and III deficiency and SDHA compound heterozygous variants." (PMID 33960148, 2021).
cholelithiasis (1 paper, 2025). The presence of crystallized deposits forming in the gallbladder or biliary tree, primarily composed of cholesterol, bilirubin, and bile. "Conversely, the expression of the following genes was positively associated with cholelithiasis risk: LIAS (OR = 1.10, 95% CI = 1.06–1.14), PNKD (OR = 1.12, 95% CI = 1.09–1.15), and SDHA (OR = 1.19, 95% CI = 1.07–1.31)." (PMID 40958306, 2025).
chordoma (1 paper, 2023). Chordomas are rare malignant tumors arising from embryonic remnants of the notochord in axial skeleton.
COVID-19 (1 paper, 2021). A disease caused by infection with severe acute respiratory syndrome coronavirus 2. "The Mann–Whitney U test showed significantly decreased levels in symptomatic COVID-19 compared to controls (NDUFA9: p = 0.04; SDHA: p = 0.01; COX4I1: p = 0.01)." (PMID 34679654, 2021). "Similarly, COVID-19 symptomatic cases also showed significantly lower expression levels of these genes compared to controls, together with a decrease in genes belonging to the mitochondrial respiratory chain subunits (NDUFA9, SDHA, COX4I1) and to mitochondrial dynamics (DNM1L, FIS1)." (PMID 34679654, 2021).
epilepsy (1 paper, 2026). A brain disorder characterized by episodes of abnormally increased neuronal discharge resulting in transient episodes of sensory or motor neurological dysfunction, or psychic dysfunction. "However, epilepsy phenotypes of these patients are ill-defined and there is only one prior report of epilepsy in a patient with SDHA deficiency." (PMID 41635801, 2026).
fibroepithelial polyp (1 paper, 2025). A polypoid lesion composed of fibrous tissue and epithelium. "The other mutations found in our case (DNMT3A, C8B, TET2, SDHA, ARID1B, NOTCH1, OR5L1, and KDM6A) do not have a known association with the formation of fibroepithelial polyps." (PMID 40936011, 2025).
gastric adenocarcinoma (1 paper, 2022). "Three Subjects with VUS were identified: SDHA: SDHA c.1579C>T in Subject 11, or SDHC:c.430G>C in Subjects 12 and 13, with respectively the diagnosis of gastric adenocarcinoma, retroperitoneal leiomyosarcoma, and uterine adenosarcoma." (PMID 36091175, 2022).
GRACILE syndrome (1 paper, 2025). GRACILE syndrome is an inherited lethal mitochondrial disorder characterized by fetal growth restriction (GR), aminoaciduria (A), cholestasis (C), iron overload (I), lactacidosis (L), and early death (E). "All other analyzed mitochondrial proteins (NDUFA9 for complex I, SDHA for complex II, Core1 for complex III, and COX1 for complex IV) were unaffected, indicating that the loss of RISP is replicated in the iPSC-derived hepatocyte and kidney tissue models of the GRACILE syndrome." (PMID 41149808, 2025).
Heat Stroke (1 paper, 2017). A condition caused by the failure of body to dissipate heat in an excessively hot environment or during PHYSICAL EXERTION in a hot environment. "When those four validated reference genes, SDHA, POLR2A, IPO8 and HMBS, were used for normalization, increased cerebral expressions of AQP4, CLDN5, OCLN, ZO1 and MMP9 were detected in heat stroke group." (PMID 28490769, 2017).
infarction (1 paper, 2025). A localised pathological necrosis of tissue resulting from obstruction of the blood supply usually by a thrombus, an embolus, or vascular torsion. "The result of WB analysis revealed an elevated expression level of SDHA protein in the peri‐infarction tissue subsequently to cerebral I/R." (PMID 40832885, 2025).
infertile (1 paper, 2022). "Representing more mild cases, a variant in SDHA has been associated with male infertility in humans, and sperm from infertile males display decreased and dispersed SDH localization." (PMID 36465130, 2022). "Thus, the provision of wild-type male sperm rescues sdha-2 hermaphrodite infertility, suggesting that oogenesis is unaffected by loss of SDHA and that defective hermaphrodite self-sperm are the cause of the fertility defect." (PMID 36465130, 2022).
Intellectual disability (1 paper, 2021). "We describe a child with compound heterozygous deleterious variants in SDHA causing reduced complexes II and III activity resulting in moderate intellectual disability and progressive cerebellar ataxia." (PMID 33960148, 2021).
keloid (1 paper, 2021). An irregularly shaped, elevated mark on the skin caused by deposits of excessive amounts of collagen during wound healing. "The expression of OxPhos complex subunits, including complexes I (NDUFA), II (SDHA), III (UQCR2), and V (ATP5A), was heterogeneous in the keloid tissues, compared to that in normal tissues." (PMID 34639105, 2021).